ALB (albumin)
Diseases named in the same sentence as ALB in open-access papers (continued):
Sharing a sentence is not in itself a finding about the gene and the disease.
Hypoalbuminemia (continued). "The most striking finding was the dynamic change in ALBs throughout hospitalization: whereas hypoalbuminemia was common on admission, interventions such as aggressive volume/albumin management or hemoconcentration in the ICU presumably led to a high prevalence of hyperalbuminemia by ICU discharge." (PMID 41226896, 2025). "For patients with severe ICH who develop hypoalbuminemia, timely supplementation of albumin or implementation of other interventions may help reduce the risk of VTE occurrence." (PMID 41573392, 2025). "Routine albumin use cannot be universally recommended; it may be considered only in severe hypoalbuminemia or refractory oedema, with careful monitoring." (PMID 41281089, 2025). "Laboratory analysis demonstrated characteristic hematological abnormalities: normocytic anemia (hemoglobin 91 g/L), significant hyperglobulinemia (serum globulin 76.18 g/L), and hypoalbuminemia (serum albumin 27.94 g/L), showing a reversed albumin-globulin (A/G) ratio of 0.37." (PMID 40901511, 2025). "Most calciphylaxis patients experience severe hypoalbuminemia, which may contribute to disease progression, as albumin—similar to fetuin-A—acts as an endogenous inhibitor of vascular calcification." (PMID 40600068, 2025). "At baseline, 10 patients (10%) had hypoalbuminemia, defined as a serum albumin level < 3.0 g/dL." (PMID 41375027, 2025). "Women with preeclampsia exhibit elevated urinary albumin excretion, leading to hypoalbuminemia." (PMID 39857389, 2025). "Prior to cycle five infusion, her albumin levels were moderately low at 23g/L which then deteriorated into severe hypoalbuminemia of 17g/L - at these levels it can be hypothesised that unbound docetaxel levels were raised, increasing toxicity risk." (PMID 41209896, 2025). "However, since albumin constitutes a substantial portion of unmeasured anions, hypoalbuminemia, common in critically ill patients, can lead to a falsely low AG, potentially misguiding clinical assessment." (PMID 41264595, 2025). "Prospective, multicenter studies should confirm whether albumin truly lacks prognostic value when contemporary critical-care practices are applied, and whether this holds in resource-limited settings where hypoalbuminemia might persist." (PMID 41226896, 2025). "The results revealed a statistically significant relationship between hypoalbuminemia (<3.5 g/dL) and the occurrence of postoperative complications (χ2 = 12.64, df = 1, p = 0.0004), indicating that patients with lower preoperative albumin levels were more likely to experience adverse outcomes." (PMID 40698225, 2025). "Misclassification with the adjustment formulas was much higher in the presence of hypoalbuminemia (ie, albumin level <30 g/L; when adjustment formulas are most likely to be used in clinical practice) compared with when albumin was normal (ie, 30-50 g/L) (eTables 5 and 6 in Supplement 1)." (PMID 39836424, 2025). "Importantly, this inflammatory environment also affects hepatic protein synthesis, leading to reduced serum albumin concentrations, thereby linking hypoalbuminemia, another component of the BAN score to metabolic stress." (PMID 41008514, 2025). "In the case series, it was possible to observe that patients often presented hypoalbuminemia (serum albumin less than 3g/dL) and an increase in the estimated glomerular filtration rate with CrCl above 130 mL/min/1.73m2, common findings in oncology and critically ill patients." (PMID 39985933, 2025). "After surgery, the dog developed hypoalbuminemia with generalized edema and was treated with transfusion of whole blood and a HSA solution of an unknown dose." (PMID 41158946, 2025). "Patients with severe forms of myocardial infarction or injury, HF, stroke, hip fracture, malignancy, and renal disease often exhibit decreased levels of serum albumin (hypoalbuminemia), which serves as a robust, reliable, and independent prognostic marker in these populations." (PMID 41305749, 2025).
Hypoalbuminemia (continued). "Median serum albumin was 3.9 (3.7-4.2) g/dl and 12.1% of patients had hypoalbuminemia." (PMID 40008735, 2025). "Notably, there was an inverse relationship between Bacteroides and ALB (r = −0.58, padj = 0.008), potentially explaining the hypoalbuminemia observed in advanced HCC through gut-derived endotoxin translocation." (PMID 41239524, 2025). "Hypoalbuminemia (albumin ≤ 35 g/L) was identified as the strongest predictor of DSS." (PMID 40337565, 2025). "Notably, early postoperative exogenous albumin supplementation was ineffective in correcting hypoalbuminemia in this study." (PMID 40740823, 2025). "Serum albumin less than 35g/L is considered as hypoalbuminemia in this study." (PMID 40161084, 2025). "Patients with hypoalbuminemia had higher mortality than those with normal albumin levels." (PMID 41009861, 2025). "The incidence of PRAKI was independently correlated with anemia (hemoglobin < 9 g/dL), hypoalbuminemia (albumin < 3.5 g/dL), systolic blood pressure, and the administration of antihypertensive medications during pregnancy, including magnesium sulfate, labetalol, and methyldopa." (PMID 40943787, 2025). "Some authors argued that preoperative albumin supplementation in selected cases (cirrhosis, multisegmental hepatectomy, or clear hypoalbuminemia) could reduce postoperative complications after liver resection." (PMID 40551534, 2025). "This could be due to small variations in albumin concentrations as all patients demonstrated some degree of hypoalbuminemia (range 17–33 g/L)." (PMID 39692515, 2025). "Additionally, inflammation or neoplastic burden itself can lead to reduced albumin synthesis, making hypoalbuminemia a recognized predictor of adverse clinical outcomes in oncology." (PMID 41283335, 2025). "Hypoalbuminemia is generally defined as a serum albumin level below 3.5 g/dL." (PMID 39860556, 2025). "Serum albumin concentrations less than 3.5 g/dL are referred to as hypoalbuminemia." (PMID 40898300, 2025). "Thus, hypoalbuminemia in preeclampsia is driven by both reduced albumin production and increased catabolism, compounded by renal impairment leading to heightened albumin excretion." (PMID 39857389, 2025). "Regarding albumin, cut-off values defining clinically relevant hypoalbuminemia remain inconsistent in the literature and the multifactorial nature of low serum albumin has brought into question whether this condition is a potentially modifiable risk factor." (PMID 40103850, 2025). "Hypoalbuminemia was defined as serum albumin levels below 35 g/L." (PMID 41488107, 2025). "CTR, in particular, showed predictive capabilities comparable to CAR, and in certain contexts—such as hypoalbuminemia or exogenous albumin administration—may offer superior clinical utility." (PMID 40566087, 2025). "Based on this case, we suggest that in OC patients experiencing mild intraoperative bleeding and minimal heart rate variation but persistent refractory hypotension, hypoalbuminemia should be considered even if preoperative biochemical tests (including serum albumin levels) are normal." (PMID 39654230, 2024). "Hypoalbuminemia is a marker of inflammation in several disease states and is further aggravated by urinary losses of albumin in nephrotic patients; it has been confirmed as a principal risk factor for the progression of CKD and cardiovascular disease in CKD patients." (PMID 38720111, 2024). "Furthermore, older adults with severe hypoalbuminemia had significantly increased death rates compared to their counterparts with normal serum albumin levels (84 (21%) vs. 11 (44%); p < 0.001)." (PMID 39493167, 2024). "Serum albumin could promptly reflect changes in the patient’s nutritional status, and hypoalbuminemia often occurred as cancer progresses." (PMID 39464703, 2024).
Hypoalbuminemia (continued). "This last finding suggests that, in addition to lowered albumin biosynthesis, hypoalbuminemia is also due to the coexistence of chronic inflammation that may oxidize albumin so reducing its blood concentration and impairing its antioxidant property." (PMID 39165413, 2024). "Hypoalbuminemia was defined as a serum albumin concentration < 30 g/L." (PMID 38540064, 2024). "In the present study, hypoalbuminemia did not appear to correlate with zinc deficiency, as both groups with low and normal zinc levels had low serum albumin." (PMID 38975455, 2024). "Moreover, patients with congenital NS can often escape after some time an albumin-dependent status despite hypoalbuminemia." (PMID 39093455, 2024). "Thirty percent of patients had hypoalbuminemia (i.e., albumin level below 35 g/L) before surgery." (PMID 38707022, 2024). "After abdominal infection, the absorption of endotoxin increases, thus stimulating the production of inflammatory mediators such as TNF, IL-1, and IL-6 in liver macrophages and inhibiting the translation of the ALB transcript, ultimately leading to hypoalbuminemia." (PMID 38166815, 2024). "Similarly, the mean CRP level was 180 mg/l ± 114.137 in patients with hypoalbuminemia compared to 116 mg/l ± 99.374 in those with normal albumin levels (P < 0.001)." (PMID 39048942, 2024). "Hypoalbuminemia is one of the most common reasons for unreasonable prescription of albumin." (PMID 39432456, 2024). "Hypoalbuminemia was defined as serum albumin levels ≤35 g/L." (PMID 39010980, 2024). "Furthermore, dogs with hypoalbuminemia (<30 g/L) exhibited significantly higher SIC than dogs with normal serum albumin levels." (PMID 38540064, 2024). "Furthermore, 1:1 propensity score matching was performed between the normal albumin level group and the hypoalbuminemia group to balance all covariates (SMD < 0.1)." (PMID 38420358, 2024). "Oxidative stress has been identified as a significant contributor to hypoalbuminemia, with the potential to induce molecular modifications in human serum albumin, including carbonylation and the formation of advanced oxidation protein products and advanced glycation end-products." (PMID 38883185, 2024). "While we could presume that low albumin levels are reflective of poor nutritional status, it is challenging to determine whether hypoalbuminemia is due to poor protein intake vs inflammatory conditions or high metabolic demands that suppress albumin synthesis." (PMID 39319797, 2024). "Multivariable binary logistic regression analysis, based on admission data, indicated patients with hypoalbuminemia (serum albumin < 3.5 g/dl) (OR: 4.03, p-value 0.014) and NLR level greater than 5.5 (OR: 4.22, p-value 0.015) are more likely to have moderate and severe PE." (PMID 38843270, 2024). "In the presence of hypoalbuminaemia, taking albumin levels into account can reveal the presence of plasma acid, which might otherwise be overlooked when relying solely on the AG or base excess values." (PMID 39357986, 2024). "ICU patients with hypoalbuminemia may experience unstable vitamin K levels when exposed to vitamin K antagonists, as these drugs primarily bind to albumin in the body." (PMID 38956732, 2024). "Of which, 19 496 were in the hypoalbuminemia group, and 23 563 had normal serum albumin levels." (PMID 38817798, 2024). "Future research could examine the potential for utilizing iso- or hypertonic albumin solutions to correct hypoalbuminemia, while simultaneously closely monitoring hemodynamics and brain-specific parameters." (PMID 39336939, 2024). "The Kaplan–Meier survival curve and log-rank test showed a significant difference between the MST of dogs with hypoalbuminemia and dogs with a normal serum albumin concentration at 64 days (95% CI, 14.39–133.61) versus 249 days (95% CI, 77.75–320.25) (p < 0.001) (Figure-3)." (PMID 38595652, 2024).
Hypoalbuminemia (continued). "This state of inflammation may lead to altered ALB levels among the population with obesity compared to healthy controls, making this condition an independent predictor of hypoalbuminemia." (PMID 38703299, 2024). "The loss of albumin through the GFB and impaired tubular reabsorption lead to hypoalbuminemia." (PMID 38398059, 2024). "Additionally, due to increased capillary permeability, albumin leaks into the interstitial space and hypoalbuminemia occurs." (PMID 39064471, 2024). "Thus, if to be pursued in future studies, ECI patients with hypoalbuminemia would appear to be the most suitable cohort in which to test albumin replenishment as a means of restoring immune function post-trauma." (PMID 39502706, 2024). "Patients with hypoalbuminemia were treated with albumin injection, 1.25 g / kg / day." (PMID 39097679, 2024). "Dogs with high-grade multicentric lymphoma treated with the L-COP protocol who had hypoalbuminemia (serum albumin concentration <2.5 mg/dL) at both pre-treatment and 4 weeks post-treatment had a significantly shorter MST than dogs with normal serum albumin levels (p < 0.001)." (PMID 38595652, 2024). "Based on this case, we recommend that if an OC patient with hypertension experiences only mild bleeding and minimal HR variation but presents with refractory hypotension, even with normal preoperative biochemical tests (including serum albumin levels), we must still suspect hypoalbuminemia." (PMID 39654230, 2024). "In the analyzed sample, low albumin values and hypoalbuminemia were found in 47% of patients." (PMID 39519455, 2024). "Our question was whether, by adding a minimal amount of extra albumin to the CPB priming solution, we would still secure the patient from possible hypoalbuminemia and low COP-caused pleural effusion." (PMID 39768615, 2024). "In addition, hypoalbuminemia, or low serum albumin levels, is a strong independent predictor of acute renal damage." (PMID 39065736, 2024). "If the effusion persists for a long time, hypoalbuminemia or hypogammaglobulinemia may occur; therefore, albumin and gammaglobulin preparations and fresh-frozen plasma are administered as required." (PMID 38903368, 2024). "Additionally, chronic malnutrition and hypoalbuminemia in patients on hemodialysis reduce albumin-bound calcium, increasing the proportion of serum free Ca2+ and weakening albumin’s buffering capacity against the rapid rise in serum Ca2+ during dialysis." (PMID 39457714, 2024). "Hypoalbuminaemia is considered to set the scene for cancer, and cancer further lowers albumin." (PMID 38918690, 2024). "Another more recent study evaluating patients admitted to the intensive coronary care unit also confirmed an increase in major bleeding events during hospitalization among patients with low albumin level and described that the pathophysiology of hypoalbuminemia is diverse and multifactorial." (PMID 37993593, 2024). "Therefore, children and adolescents with NS that have hypoalbuminemia should be screened for hypothyroidism and the treating clinicians should endeavor to achieve and maintain normal albumin levels in these patients." (PMID 38373933, 2024). "Unlike other risk factors, hypoalbuminemia is a risk factor that can be quickly corrected in the short term through the administration of human serum albumin." (PMID 39723253, 2024). "Additionally, high interleukin-6 levels produced by cancer cells inhibit the synthesis of albumin, resulting in hypoalbuminemia." (PMID 38791922, 2024). "The median albumin level was 3.45 (3.00–3.78) g/dL, with 89.29% (n = 25) with hypoalbuminemia." (PMID 38592101, 2024). "Furthermore, Li+ sick dogs presenting hypoalbuminemia showed higher MLR ratios than animals with normal albumin values." (PMID 39444011, 2024). "Lastly, low albumin levels (hypoalbuminemia) posed a risk not just for the early discontinuation of chemotherapy but also as an independent prognostic factor within the chemotherapy group." (PMID 39195131, 2024).
Hypoalbuminemia (continued). "The involvement of early and progressive hypocalcemia and hypoalbuminemia in severe COVID-19 could be due to UFAs binding to both albumin (ALB) and calcium." (PMID 38397885, 2024). "Additionally, there is an increased capillary permeability, resulting in the escape of albumin into the interstitial space, further driving hypoalbuminemia." (PMID 38398059, 2024). "Also, patients who had a serum CRP level above 10 mg/dL and ALB below 3.5 mg/dL, corresponding to an increased inflammatory status and a progressive nutritional decline, were included in the hypoalbuminemia." (PMID 39000088, 2024). "Non‐gastrointestinal causes of hypoalbuminemia, defined by a serum albumin ≤2.8 g/dL, were ruled out prior to enrollment." (PMID 38053473, 2023). "Albumin may be more beneficial for specific sepsis subgroups, such as those with hypoalbuminemia, hypervolemia, advanced liver disease, or kidney failure." (PMID 38139434, 2023). "Another relevant marker of poor prognosis is hypoalbuminemia, defined as decreased levels of serum albumin (typically below 3.5 g/dL), and has been correlated with worse outcomes in advanced stages and may be a potential predictor of post-surgical survival." (PMID 36837431, 2023). "In general, hypoalbuminemia may lead to the increase of Vd of highly albumin-bound antibiotics and hydrophilic drugs (e.g., streptomycin) and to the decrease of Vd of the α1-acid glycoprotein-bound drugs (e.g., rifabutin)." (PMID 37371728, 2023). "Moreover, the common characteristic of the death was hypoalbuminemia, whose serum albumin was decreased at an extremely low level postoperatively." (PMID 38066484, 2023). "Clinical research has revealed that continuous albumin supplementation for 3 or more consecutive days inhibits the hypercoagulable state of patients with COVID‐19 and improves the prognosis of patients with COVID‐19 and hypoalbuminemia." (PMID 38020714, 2023). "This may explain the high rate of peritonitis, as the mean and first-year mean albumin values were detected in the patient group with prolonged hypoalbuminemia in this study." (PMID 36762995, 2023). "HAV KUMC 19–1 showed hypoalbuminemia with serum albumin levels of < 3.5 g/dl." (PMID 37437048, 2023). "Clinical studies suggest that the underlying cause of hypoalbuminemia, rather than solely low albumin levels, is accountable for the associated morbidity and mortality." (PMID 38187790, 2023). "It is noteworthy that other medical conditions can lead to severe hypoalbuminemia (e.g., advanced kidney disease or liver disease), yet treating the albumin deficiency through albumin infusion typically leads to little or no measurable benefit." (PMID 36979342, 2023). "This could be due to the frequent monitoring of albumin levels in both groups and intravenous albumin treatment was administered to patients with hypoalbuminemia." (PMID 38107705, 2023). "On the one hand, hyperinflammation in COVID-19 may lead to reduced albumin synthesis and hypoalbuminemia, on the other hand, low albumin levels may result from high clearance of damaged and oxidized albumin." (PMID 36982882, 2023). "Nephrotic syndrome was diagnosed based on the following: 24 h urine protein > 40 mg/m2/h or spot urine protein, creatinine ratio > 200 mg/mmol, hypoalbuminemia (serum albumin < 25 g/L), generalized oedema, and hypercholesterolemia (serum cholesterol > 5.2 mmol/L)." (PMID 38137694, 2023). "The patient with maximum ferritin concentration above 33,511.2 ng/mL developed liver dysfunction with coagulation disorders requiring multiple transfusions of fresh frozen plasma (FFP), Octaplex® and cryoprecipitate, and hypoalbuminemia treated with numerous albumin infusions." (PMID 38137714, 2023). "Reduced serum albumin concentrations in the challenged chickens and control group may also be due to liver lesions as hypoalbuminemia is indicative of reduced liver function." (PMID 37500690, 2023).